CYB561D1 (cytochrome b561 family member D1)
Description:
Probable transmembrane reductase that may use ascorbate as an electron donor and transfer electrons across membranes to reduce monodehydro-L-ascorbate radical and iron cations Fe(3+) in another cellular compartment.
Synonyms: FLJ39035; FLJ44753
Tractability: Antibody: UniProt predicts a signal peptide or a membrane-spanning region.
Gene: Protein-coding gene on chromosome 1 (109,494,052 to 109,502,932, forward strand). Ensembl gene ENSG00000174151.
Subcellular location: Membrane
Gene Ontology:
Molecular function: protein binding; oxidoreductase activity; transmembrane ascorbate ferrireductase activity
Biological process: transmembrane transport
Cellular component: endoplasmic reticulum membrane; membrane
Genetic constraint (gnomAD): Loss-of-function variants: 15 observed, 19.48 expected, observed/expected ratio (o/e) 0.77, 90% interval 0.51 to 1.19. The upper end of that interval is the gene's LOEUF score, 1.19, which puts it in group 5 of 6, group 1 being the genes least tolerant of losing a copy. Missense variants: 297 observed, 285.33 expected, observed/expected ratio (o/e) 1.04, 90% interval 0.95 to 1.15. Synonymous variants: 133 observed, 114.43 expected, observed/expected ratio (o/e) 1.16, 90% interval 1.01 to 1.34.
Homologues: Orthologues: chimpanzee CYB561D1 (95% identical), macaque CYB561D1 (94% identical), pig CYB561D1 (93% identical), rabbit CYB561D1 (93% identical), dog CYB561D1 (92% identical), guinea pig CYB561D1 (91% identical), mouse Cyb561d1 (90% identical), rat Cyb561d1 (90% identical), tropical clawed frog cyb561d1 (61% identical), zebrafish cyb561d1 (49% identical), Drosophila melanogaster CG10165 (22% identical), Drosophila melanogaster CG13077 (19% identical), and 1 more. Paralogues in human: CYB561D2 (49% identical).
Diseases named in the same sentence as CYB561D1 in open-access papers:
CYB561D1 is named in the same sentence as 5 diseases in open-access papers, as found by Europe PMC text mining. Sharing a sentence is not in itself a finding about the gene and the disease. The quoted sentences say what the papers report.
COVID-19 (1 paper, 2023). A disease caused by infection with severe acute respiratory syndrome coronavirus 2. "Mitochondrial proteins such as ATP5A1, CYB561D1, several CYP accessions, L2HGDH, two MRP, MRPL37, NDUFS1 and others showed increased observation frequency across COVID-19 and ICU-ARDS versus NHP individually by the Chi Square test (χ2 ≥ 10, p ≤ 0.01) and as a group by one way ANOVA (p ≤ 0.003)." (PMID 37031181, 2023).
lung carcinoma (1 paper, 2023). "So far, there have been no reports on other three down regulated mRNAs (KCND3, SCN1A and CYB561D1) in lung cancer targeted by miRNAs." (PMID 37185598, 2023).
CYB561D1 also shares sentences with these, for which no sentence is quoted: adenocarcinoma (1 paper); squamous cell carcinoma (1); tumor (1).